SLC1A5 (solute carrier family 1 member 5)
Diseases named in the same sentence as SLC1A5 in open-access papers (continued):
Sharing a sentence is not in itself a finding about the gene and the disease.
cancer (continued). "While investigating the mechanism by which ABCG2 enhances survival in stressful milieus, we have identified a physical and functional interaction between ABCG2 and SLC1A5, a member of the solute transporter superfamily and the primary transporter of glutamine in cancer cells." (PMID 38641063, 2024). "SLC1A5 is a target gene of the c-Myc oncoprotein as well as the pRb/E2F tumor suppressor pathway, which has led to a deep interest in characterizing its role in tumorigenesis and cancer biology." (PMID 39062801, 2024). "However, despite the critical role of SLC1A5 in cancer initiation and development, the potential regulatory mechanism of SLC1A5 involving lncRNAs remained incompletely understood." (PMID 39440055, 2024). "Quercetin/SLC1A5 axis also increases the iron content in cancer cells." (PMID 38705513, 2024). "Similarly, HCV infection upregulates SLC1A5 to drive glutamine addiction in cancer cells, and a recent study demonstrated that SLC1A5 membrane localization increases the presence of hACE2 receptors able to bind the SARS-CoV-2-RBD." (PMID 38905309, 2024). "Inhibition of SLC1A5 by quercetin in CRC promotes sensitivity of cancer cells to chemotherapy." (PMID 38705513, 2024). "Therefore, we conducted a comprehensive investigation to further explore the relationship between SLC1A5 expression and patient outcomes in cancer." (PMID 37566748, 2023). "In most cancers, the expression of SLC1A5 is positively correlated with the infiltration of macrophages, CD4+ T cells, CD8+ T cells, dendritic cells, monocytes, MDSCs, and CAFs and negatively correlated with the infiltration of monocyte, HSC and Endo progenitors." (PMID 37566748, 2023). "We predicted through bioinformatics analysis that SLC1A5 is involved in regulating the tumor microenvironment in most cancer types and is closely related to immune cell infiltration, but the importance of SLC1A5 has been experimentally confirmed in only a few cancer types." (PMID 37566748, 2023). "Through the analysis of drugs whose sensitivity may be related to SLC1A5 expression, we found that ingenol, prostratin, and parthenolide can be used as potential small molecule drugs for cancer treatment." (PMID 37566748, 2023). "Recently, studies have indicated that suppressing SLC1A5 by RNA interference or pharmacological inhibition can effectively prevent cancer development and progression in human AML xenograft mouse models, which appears to be associated with glutamine uptake and mTORC1 pathway." (PMID 37249801, 2023). "In addition, we performed genomic alteration analysis, prognosis analysis, gene set enrichment analysis (GSEA), immune cell infiltration analysis and drug sensitivity analysis based on SLC1A5 expression across cancers." (PMID 37566748, 2023). "The results showed that SLC1A5 was upregulated in most cancer types." (PMID 37566748, 2023). "Previous studies have indicated that SLC1A5 might affect how immune cells behave and infiltrate tumor microenvironment, which can promote cancer." (PMID 37818360, 2023). "Therefore, we comprehensively analyzed the expression level of SLC1A5 across cancers and compared it with that in normal tissues." (PMID 37566748, 2023). "This suggests that SLC1A5 plays different roles in different cancer types." (PMID 37566748, 2023). "SLC1A5 is important for the metabolism of L-glutamine, which necessary for developing cancer cells." (PMID 37587156, 2023). "Consequently, SLC1A5 is expressed in highly proliferative cells such as inflammatory, stem and cancer cells to meet their augmented glutamine demand." (PMID 37858220, 2023). "In addition, epithelial-mesenchymal transition, oxidative phosphorylation, unfolded protein response, MYC targets, and MTORC1 signaling are closely related to the expression of SLC1A5 in cancer." (PMID 37566748, 2023). "SLC1A5 has been identified as a candidate therapeutic target for cancer." (PMID 37928274, 2023). "We also investigated how TRIM6 regulated SLC1A5 in H460 cancer cells." (PMID 36654781, 2023).
cancer (continued). "SLC1A5 is upregulated in variety of cancers, promoting glutamine metabolism." (PMID 37599427, 2023). "SLC1A5 is a glutamine transporter crucial to the functioning of cancer cells." (PMID 37928274, 2023). "The high-expression levels of SLC1A5 have been reported to be overexpressed in many human cancers." (PMID 35237783, 2022). "Besides acting as a positive regulatory gene of ferroptosis against cancer, another identity of SLC1A5 is that it is a glutamine transporter." (PMID 35419359, 2022). "In this work, the overexpression of SLC1A5 could significantly increase the expressions of effector molecules of the mTORC1 pathway, revealing the close relationship between the cancer-promoting abilities of SLC1A5 and mTORC1 signaling pathway." (PMID 35419359, 2022). "SLC1A5 is one of the most important transporters used by cancer cells to take up glutamine." (PMID 35008407, 2022). "Given that MYC, SLC1A5, and mTORC1 levels are higher in glutamine-addicted cancer cells, along with glutaminase levels, all of these can be exploited in future clinical studies as biomarkers to identify patients when assessing the potential effectiveness of glutaminolysis inhibitors." (PMID 36499623, 2022). "Taken together, the data suggest that targeting SLC1A5 may be an effective therapeutic target for cancer treatment, particularly to target glutamine metabolism and cell biological behavior." (PMID 35041678, 2022). "SLC1A5, a ferroptosis regulator gene, plays a dual role in cancer regulation." (PMID 35419359, 2022). "Taking these findings together, SLC1A5 has a dual role in cancer regulation." (PMID 35419359, 2022). "It has been shown that amino acid transporters can be regulated by m6A modification, as the main glutamine transporter SLC1A5 in cancer cells can be regulated by the m6A modified demethylase FTO and SLC7A11 is promoted to decay by preferentially bound to YTHDC2." (PMID 35054897, 2022). "Cancer cells maintain high pools of glutamine by upregulating the expression of glutamine transporters, such as Alanine/Serine/Cysteine/Threonine Transporter 2 (ASCT2; SLC1A5) in PC and SLC7A5 in HC." (PMID 36618350, 2022). "Of note, SLC1A5 is a promising therapeutic target for restricting cancer progression." (PMID 36090030, 2022). "Given that tumor-associated macrophages (TAMs) can mediate cancer metastasis, chemotherapeutic resistance, and immune evasion through secreting CD24, CXCL8, CCL2, and other cytokines, SLC1A5 is probably involved in the formation of the immune-tolerant microenvironment." (PMID 35419359, 2022). "However, recent studies showed that ASCT2/SLC1A5-deficient mice exhibit normal growth and survival, indicating that targeting of ASCT2 for cancer therapy is likely to be well tolerated and elicit few adverse effects." (PMID 35418865, 2022). "The most studied transporters for their role in cancer include SLC1A5 (alanine–serine–cysteine transporter 2 or ASCT2), SLC7A5 (system L amino acid transporter 1 or LAT1), SLC7A11 (system x−c transporter or xCT), and SLC6A14 (amino acid transporter B0,+ or ATB0,+)." (PMID 34704597, 2021). "Several studies demonstrate that the knockdown of SLC1A5 prevents glutamine uptake which in turn inhibits cell proliferation, indicating the importance of this solute carrier during tumorigenesis in different types of cancer." (PMID 34282517, 2021). "However, our results clearly indicate that SLC1A5 can serve as a prognostic biomarker in diverse cancers, including HCC." (PMID 34367941, 2021). "Given the emerging role of SLC1A5 as a promising cancer biomarker, SLC1A5-specific tracers could be further developed into precision PET imaging diagnostic tools." (PMID 33401748, 2021). "These cancers with high SLC1A5 expression may be dependent on glutamine and respond to glutamine inhibitors, either alone or in combination with other therapies." (PMID 34367941, 2021).
cancer (continued). "Furthermore, it has been demonstrated that SLC38A1/SNAT1 and SLC38A2/SNAT2 activity is essential to mediate net glutamine uptake and glutaminolysis in cancer cells, whereas SLC1A5/ASCT2 and SLC7A5/LAT1 coordinate intracellular amino acid pools." (PMID 34003553, 2021). "One major component that supports cancer cells in the uptake of GLN is SLC1A5." (PMID 34503536, 2021). "The extent of SLC1A5 expression correlated significantly with tumor purity in 20 types of cancer." (PMID 34367941, 2021). "Thus, some experiments need to be performed in vivo/in vitro, and single-cell RNA sequencing should be carried out to clarify the different role of SLC1A5 in immune and cancer cells." (PMID 34367941, 2021). "SLC1A5 is a mitochondrial glutamine transporter in cancer metabolic reprogramming." (PMID 34530825, 2021). "Our study demonstrated that in most cancer types, SLC1A5, SLC7A5, SLC7A11, and SLC3A2 were highly expressed and indicative of poorer survival outcomes, while the effects of changes in the expression of GLS2 and GLS depended on the type of cancer under consideration." (PMID 34573287, 2021). "SLC1A5 is highly expressed in many types of cancers, such as breast, pancreatic, and colon cancers." (PMID 34503536, 2021). "Further, we demonstrated the prognostic value of SLC1A5 in pan-cancer." (PMID 34367941, 2021). "Although inhibition of SLC1A5 failed to affect HCC proliferation, a variant of SLC1A5 was found to be a gatekeeper for glutamine metabolism and metabolic reprogramming in cancer cells." (PMID 34367941, 2021). "In addition, SLC1A5 (ASCT2), SLC7A5 (LAT1), SLC7A11 (xCT), and SLC6A14 (ATB0+) have been shown to be positively expressed in cancer." (PMID 33937189, 2021). "SLC1A5 expression is decreased by the tumor suppressor RB, supporting its role in cancer growth." (PMID 31980738, 2020). "Among these genes, the glutamine transporter SLC1A5 (also known as ASCT2) was verified as a miR-634 target gene in A431 cells; ASCT2-dependent glutamine uptake and subsequent glutaminolysis metabolism, which involves glutamine utilization, are essential for cancer cell survival and proliferation." (PMID 33294587, 2020). "In addition, SLC1A5 was shown to have clinical importance, and it is considered the most critical plasma membrane glutamine transporter in cancer cells." (PMID 32943735, 2020). "SLC1A5 acts as a high-affinity transporter of l-glutamine in rapidly growing cancer cells." (PMID 32993179, 2020). "One such transporter, SLC1A5, is highly expressed in cancer cells." (PMID 33374949, 2020). "Glutamine transporters, such as SLC1A5 (also known as ASCT2), are up-regulated in various cancers." (PMID 29784041, 2018). "Indeed, blocking of SLC1A5 has been shown to diminish or prevent tumor cell proliferation in different cancers." (PMID 28553292, 2017). "SLC1A5 has been recently described as a novel target for the treatment of a variety of cancers, and our results indicate that inhibition of SLC1A5 in cancer therapy may be tolerated well by the immune system of cancer patients." (PMID 28553292, 2017). "SLC1A5 (solute carrier family 1, member 5) is a small neutral amino acid exchanger that is upregulated in rapidly proliferating lymphocytes but also in many primary human cancers." (PMID 28553292, 2017). "SLC1A5 (also known as ASCT2) is the most described glutamine transporter in cancer cells." (PMID 27344174, 2016). "To evaluate whether a defect in glycosylation could influence Gln metabolism, we first examined whether ASCT2 (SLC1A5), described as the main Gln transporter in cancer cells, could be affected by Glc deprivation." (PMID 27344174, 2016). "Import of glutamine into cancer cells is exerted by SLC1A5 (ASCT2)." (PMID 27418963, 2016).
cancer (continued). "The inhibition of glucose utilization is accompanied by a down-regulatory effect of STS on the glutamine transporters Slc1a5 and glutaminase, which catalyze glutamine catabolism and provide cancer cells with bio-synthetic precursors for aminoacids and DNA synthesis." (PMID 25909219, 2015). "Besides its significance in prognosis, the value of SLC1A5 in cancer treatment has also drawn more and more attention these years." (PMID 26599282, 2015). "However, although SLC1A5 is the major glutamine transporter, with high affinity and high capacity observed in many cancer types, other members of the solute carrier superfamily including SLC7A5 (LAT1) and SLC38A1/2 (SNAT1/2) have also been linked to tumor-specific glutamine uptake." (PMID 38641063, 2024). "Given the crucial role of SLC1A5-regulated Gln uptake in tumor cell metabolism and ferroptosis, targeting Gln transport through the regulation of SLC1A5 could potentially serve as a therapy for cancers." (PMID 38388534, 2024). "Additionally, SLC1A5 is a significant transporter of serine in cancer cells." (PMID 39958609, 2024). "Therefore, pancancer studies on the cancer biology of SLC1A5 are urgently needed." (PMID 37566748, 2023). "In addition, many cancer cells become dependent on glutamine, leading to what is called glutamine addiction, which is described as a high glutaminolytic flux rate, wherein the glutamine transporter, ASCT2 (SLC1A5), transfers glutamine into the cytoplasm." (PMID 34287243, 2021). "One possible mechanism for the explanation of the correlation detected between SLC1A5 expression and poor prognosis might be that SLC1A5 contributes to cancer cell uptake of glutamine, which led to activation of the mTORC1 pathway as well as promotion of cancer cell proliferation." (PMID 34367941, 2021). "In addition, SLC1A5 mRNA correlated significantly with the extent of infiltration of B cells in 14 cancer types, CD4+ cells in 15 cancer types, CD8+ cells in 12 cancer types, DC in 20 cancer types, macrophages in 17 cancer types, and neutrophils in 17 cancer types." (PMID 34367941, 2021). "Considering that the SLC1A5 variant is an important regulator of the production of glutamine-derived α-KG16, confirming whether epigenetic regulation by glutamine-derived α-KG is affected by the SLC1A5 variant in cancer cells or stem cells is necessary." (PMID 32943735, 2020). "Therefore, SLC1A5 functions as an oncogene in multiple human cancers." (PMID 31409775, 2019). "Several amino acid transporters, including the transporters for glutamine (SLC1A5/ASCT2) and leucine (SLC7A5/LAT1, which imports Leu in exchange for Gln efflux by SLC3A2/CD98/4F2hc), have been linked to mTORC1 activation and their overexpression is often associated with malignancies." (PMID 31817676, 2019). "Likewise, ASCT2/SLC1A5 is also elevated in numerous cancers." (PMID 30241549, 2018). "Furthermore, cancer cell lines have been shown to require SLC1A5 for their survival in vitro." (PMID 28553292, 2017). "The remaining nine surface proteins identified solely (ANTXR1, AG1, DCBLD2, EFNB1, EMB, OSMR, SLC1A5) or found upregulated (ATP1B3 and ITGB1) on the MCF10A surface had no direct association with embryonic development signaling in the context of KRas mutant signaling in cancer cell lines." (PMID 27894102, 2016). "In cancer cells, glutamine is transported into cell through the amino acid transporter ASCT2/SLC1A5." (PMID 39806421, 2025). "Data from the human Cancer Cell Line Encyclopedia (CCLE) demonstrated differential expression of these genes across cell lines, with high expression of PHGDH, PSAT1, SLC1A5 and SLC38A2, and low expression of SLC38A4 and SLC7A10." (PMID 40660426, 2025). "Critically, PHGDH, PSAT1, PSPH, SLC1A4, SLC1A5 and SLC38A2 show robust co‐expression patterns in both TCGA tumour samples and CCLE cancer cell lines, suggesting coregulated functionality." (PMID 40660426, 2025).
cancer (continued). "The regulation of some SLCs, such as SLC7A11, SLC1A5, and SLC38A9, are involved in cancer progression." (PMID 39949345, 2025). "The multidrug resistance-associated gene ABC transporter ABCG2 can form a complex with SLC1A5 in MCF-7 cells to facilitate glutamine influx and enhance redox regulation, providing a survival advantage to cancer cells under oxidative stress." (PMID 39973065, 2025). "Specifically, genes promoting glutamine–glutathione transition, including glutaminase 1, SLC1A5, K-Ras, γ-glutamylcysteine ligase, c-Myc, and NRF2, showed reduced expression, leading to excessive cellular ROS level and enhanced cancer cell apoptosis." (PMID 40649322, 2025). "Numerous cancer cells depend on glutamine, unless they express GS, making Alanine-serine-cysteine (ASC) amino acid transporter 2 (ASCT2; SLC1A5) a potential target for cancer chemotherapy." (PMID 38879519, 2024). "Both the Na+/amino acid exchanger SLC1A5 and the unidirectional Na+/Cl-/amino acid isotropic transporter protein SLC6A14 are regulated by MYC and are often overexpressed in various types of cancer." (PMID 39051546, 2024). "Glutamine consumption is enhanced in cancer cells, and high expression of SLC1A5 (ASCT2), the major glutamine transporter, is correlated both to the levels of MYCN as well as the activating transcription factor 4 (ATF4) in NB cells." (PMID 39101440, 2024). "Glutamine is transported into and out of cancer cells via specific transporters, such as SLC1A5 (ASCT2) and SLC7A5 (LAT1), which play integral roles in sustaining the increasing glutamine demands of proliferating cancer cells." (PMID 38473414, 2024). "Similar to cancer cells, activated T cells upregulate glutamine transporters (including SLC1A5/ASCT2 and SLC38A1/SNAT1) and increase glutaminolysis to accommodate the demands of rapid proliferation." (PMID 39211039, 2024). "SLC1A5, also known as alanine, serine, cysteine-preferring transporter 2 (ASCT2), mediates glutamine uptake, an essential amino acid for cancer cells." (PMID 38705513, 2024). "The observation that ABCG2 interacts with the amino acid transporter SLC1A5 to regulate glutamine metabolism suggests a new and previously unexplored role for ABCG2 in the regulation of cancer cell survival." (PMID 38641063, 2024). "Remarkably, IGF2BP2 regulates glutamine uptake and metabolism by upregulating MYC, glutamic–pyruvic transaminase 2 (GPT2), and solute carrier family 1 member 5 (SLC1A5) in AML, demonstrating that IGF2BP2s can influence amino acid metabolism in cancer." (PMID 39596216, 2024). "Through the overexpression of SLC1A5, glutamine absorption is increased in K-Ras-driven cells, similar to the results observed in MYC-driven cancer cells." (PMID 39051546, 2024). "Receptors for SLC1A5 (ASCT2) and SLC38A5 glutamine transporters are hyper-expressed in some cancers, and their pharmacological inhibition blocks tumor growth." (PMID 39119332, 2024). "The Na+ gradient is used to import glutamine and other amino acids into cancer cells via SLC1a5/ASCT2, which is upregulated and highly active in many cancer types." (PMID 36183245, 2023). "It's previously reported that SLC1A5, SLC7A11, and GCLM are negative regulators that restrain ferroptosis in some kinds of cancers, while the remaining SAT1 facilitates ferroptosis." (PMID 35841206, 2023). "Cancer cells derive endogenous glutamine from glutamine synthetase (GLUL) and transport exogenous glutamine into the cell by SLC1A5 (also known as ASCT2)." (PMID 37420266, 2023). "Alanine, serine, and cysteine transporter 2 (ASCT2), also known as SLC1A5, is an amino acid transporter that is upregulated in many cancers, including KRAS-mutant CRC." (PMID 37576895, 2023). "Among them, ASCT2 (SLC1A5), SNAT1 (SLC38A1) and SNAT2 (SLC38A2) play a major role in cancer cells, since ASCT2 is required for optimal growth at low glutamine concentrations, whereas SNAT1 and SNAT2 mainly mediate net glutamine uptake for glutaminolysis." (PMID 36768660, 2023).